HIF1A (hypoxia inducible factor 1 subunit alpha)
Diseases named in the same sentence as HIF1A in open-access papers (continued):
Sharing a sentence is not in itself a finding about the gene and the disease.
cancer (continued). "HIF1α mRNA was found elevated in pre-neoplastic breast, colon, and prostate lesions and remained elevated when cells were cultured in normoxic conditions, which further suggests that hypoxia is not necessary for HIF-1α activation in cancer cells." (PMID 36079025, 2022). "As JNK and p38 MAPK pathway activation regulates HIF-1α expression, inhibition of these pathways by Celastrol may infer a negative effect on HIF-1α mediated cancer progression." (PMID 36014432, 2022). "Moreover, quercetin significantly inhibited HIF-1 transcriptional activity without altering the mRNA and protein levels of HIF-1α and sensitized HCT116 cancer cells to cisplatin and etoposide under hypoxic conditions." (PMID 35890106, 2022). "As cancer cells are frequently exposed to a hypoxic environment and are often under oxidative stress, it would be interesting to know how interaction between BTG3 and HIF-1α is regulated in normal, as opposed to cancer cells, under these conditions." (PMID 33311481, 2020). "However, at least in our model, metabolic reprogramming was induced without changes in HIF-1α and HIF-2α stabilization or in the involvement of cancer-derived EVs, suggesting that other humoral factors are associated with the glucose metabolism of fibroblasts." (PMID 32555715, 2020). "It is conceivable to hypothesize that, in pathological or cancer staging events when these stress conditions are not completely established (lower concentration of ROS and/or not hypoxia conditions), the STAT3/HIF-1α/PKM2 axis may not be yet active." (PMID 31500219, 2019). "In addition, the LETM1 expression is correlated with cancer stemness-related gene LGR5 (p < 0.001) and HIF1α expression (p < 0.001), but not with others." (PMID 31500591, 2019). "Given that the interplay between HIF-1α and PGC-1α is not fully elucidated, and that HIF-1α has major functions in tumorigenesis and metastasis, it would be important to determine how HIF-1α can influence the outcome of PGC-1α in other cancer models." (PMID 29629336, 2018). "However, to our knowledge, impairment of hypoxia-induced HIF-1α expression and VEGF-A secretion upon RICTOR blockade in cancer cell lines has not been reported so far." (PMID 28445935, 2017). "Nevertheless, while the downregulation of mitochondrial respiration by HIF-1 is certainly a valid mechanism for adaptation of cancer cells to low oxygen tension, the block of OXPHOS may not be severe, since this would lead to HIF-1α destabilization." (PMID 29230384, 2017). "While HIF-1α activation resulted in attenuated cell growth in CD90+ PEO1 cells and promoted cell survival this could not account for why the cancer stem-like cells presented growth advantages under high ammonia." (PMID 29383096, 2017). "However, HIF-1α and BNIP3 did not influence the cytotoxicity of Celastrol because the main mechanism by which Celastrol kills cancer cells is through stimulating ROS-mediated JNK activation and inducing apoptosis." (PMID 25383959, 2014). "Even though HIF-1α and HIF-2α are dominantly expressed in cancer cells, our present data could not exclude that the HIF-3α was also involved in PIM2 regulation." (PMID 24505470, 2014). "Moreover, starvation also can induce HIF-1α expression in HUVEC as well as in various cancer cell types examined, indicating that this effect is a general action, and not specific to cancer cells only." (PMID 25115400, 2014). "However, both HIF-1α and PGK1 were found to be down-regulated in CSC-like cancer cells compared to non-CSC cancer cells." (PMID 24423398, 2013). "So, why is the expression of HIF-1α decreased in perinecrotic regions (pimonidazole-positive/HIF-1α-negative layer), although cancer cells should be exposed to lower O2 conditions there compared to the HIF1α-positive/pimonidazole-negative regions because of the distance from blood vessels?" (PMID 23203043, 2012).
cancer (continued). "Interestingly, the overexpression of HIF-1α and activation of HIF pathways are observed in tumor cells due to lack of HIF-α ubiquitination and degradation in cancer patients." (PMID 21689478, 2011). "Similarly, USP28 could stabilize HIF-1α by antagonizing FBXW7 rather than interacting with HIF-1α, which impacts the cancer cell activity and capillary formation." (PMID 35814468, 2022). "In addition, the radioprotective mechanisms mediated by HSP90 and HIF-1α may attenuate the cytotoxic effects of carbon ion beams on CSCs and hypoxia-adapted non-stem cancer cells, but the inhibition of HSP90 or HIF-1α enables the enhancement of those effects." (PMID 33806538, 2021). "However, expression of VHL was not regulated by SCG2 in cancer cells, suggesting that SCG2 may promote the role of HIF‐1α in ubiquity degradation via binding VHL." (PMID 34160138, 2021). "However, due to cancer heterogeneity, HCC patients suffered from quite different outcome after TACE, which indicated that hypoxia was not the only reason for aberrant overexpression of HIF-1α after TACE." (PMID 31942180, 2020). "Therefore, non-amplification mechanisms, such as activation of HIF1α, may work either independently or in concert with gene amplification to drive a high level of CD24 expression in cancer." (PMID 31244889, 2019). "In contrast, in the absence of oxygen, HIF-1α is stabilized, dimerizes with HIF-1β, and the HIF heterodimers translocate to the nucleus where it activates the transcription of various downstream targets, many of which are known to be involved in cancer aggressiveness and chemoresistance." (PMID 30347860, 2018). "Specifically, activation of the HIF-1α/miR-210/ISCU signaling pathway has not been demonstrated in most cancer types and whether cancer cells coordinately activate hypoxia/HIF-related pH-regulating proteins and the miR-210/ISCU signaling axis is presently unknown." (PMID 28099149, 2017). "HIF-1α isoforms containing a three base pairs TAG insertion between exon 1 and exon 2 (designated HIF-1αTAG) and HIF-1α736 mRNAs were found expressed at higher levels in oestrogen receptor (OR)-negative carcinomas compared to normal/benign tissues (P = 0.009 and P = 0.004 respectively)." (PMID 20624301, 2010). "Importantly, we revealed that photoactivated ZQX-1 activated HIF1A survival signaling and DNAJB11 mediated survival signaling in A549 cells, though both survival signaling pathways could not compete with oncosis and apoptosis signaling to rescue cancer cells." (PMID 37175463, 2023). "In addition, it was observed that cetuximab could clearly downregulate HIF-1α levels in cancer cells that were sensitive to EGFR inhibition and it was shown that HIF-1α was required, although it might not be sufficient, to mediate the response of cancer cells to cetuximab." (PMID 26032726, 2015).
infection (374 papers, 2008 to 2026). The state of being infected such as from the introduction of a foreign agent such as serum, vaccine, antigenic substance or organism. "Particularly, the expression of granule protease and cathelicidin was significantly reduced in HIF-1α–deficient neutrophils, which is associated with diminished bactericidal activity in vitro and inability to fight infection in in vivo." (PMID 40708812, 2025). "During pathogenic infections, the HIF1α pathway is rapidly induced to meet the metabolic needs for defense." (PMID 40387431, 2025). "Long-term post-MHV-1 infection was associated with increased protein levels of HIF1-α, TLR-2, and EGFR, as revealed by immunoblot investigations." (PMID 38672267, 2024). "Similar to M. marinum, mice with genetic deficiency of HIF-1α in their myeloid cells also resulted in increased bacterial burden and necrotic granulomas upon infection by M. avium." (PMID 39119289, 2024). "It is worth noting that in the case of infection, not only LPS stimulates the expression of genes encoding HIF-1α, but also local metabolic acidosis resulting from the infection." (PMID 39456823, 2024). "HIF-1α knockdown reduces inflammation caused by PSCV infection in MH-S and THP-1 cells and lowers elevated levels of CTGF, COLA1, and α-SMA in MRC-5 cells exposed to CPMSCV." (PMID 38914619, 2024). "Research showed that deficiency of HIF-1α in macrophages promoted metabolic reprogramming and polarization during infection." (PMID 38555419, 2024). "Inhibition of HIF1α accumulation by siRNA knockdown or with a small molecule inhibitor significantly reduced host cell invasion and prevented the infection-induced expression of genes encoding pro-inflammatory proteins including cytokines and chemokines." (PMID 38902255, 2024). "Previous studies have reported that HIF-1α-mediated glycolysis is closely associated with infection of host cells by many viruses, such as SARS-CoV-2, WSSV, and ARV (21, –, 23)." (PMID 37796013, 2023). "Following LPS or LPS and IFNγ stimulation during infection, macrophages showed high levels of HIF1α and, accordingly, HIF1α deficiency affects glycolytic activity in murine macrophages." (PMID 37895302, 2023). "The expression of HIF-1α, Relish and Stat5b were significantly upregulated in the susceptible family at 0 and 6 h post-infection, demonstrating that these genes are potentially involved in defense and immune response of the susceptible family." (PMID 37143674, 2023). "For example, it is important that HIF-1α–associated metabolic adaptation to infection includes upregulation of glycolysis to maintain intracellular ATP and NADH needed for tissue function and host immune activation." (PMID 37417946, 2023). "Myeloid cells deficient in HIF-1α mice are more susceptible to infection, fail to restrict the systemic spread of infection, and reduce phagocytes’ killing ability against Gram-negative and Gram-positive bacteria." (PMID 34898382, 2022). "In general, loss of HIF1α signaling is associated with an infection response that is low in neutrophils and high in eosinophils." (PMID 36324747, 2022). "It was reported that during infection with human pathogenic bacteria, bacterial siderophores are implicated in hypoxia-independent activation of the transcription factor HIF-1α." (PMID 33805299, 2021). "Inhibition of HIF-1α makes Drosophila more susceptible to death by inflammation after infection, suggesting that HIF-1α is involved in an important process of negative feedback inhibition on the NF-κB dependent defensive mechanism to achieve moderate immunity." (PMID 33763034, 2021). "Among the differences in the autophagy/LAP regulation, there was a significant downregulation of Deptor transcript and the upregulation of Hif1α transcript after infection in BMDCs from the susceptible strain." (PMID 33255176, 2020).
infection (continued). "Increase in EC permeability was also present in infections with capsule-deficient mutants in line with induction of HIF-1α and VEGF by these strains (online resource)." (PMID 32529267, 2020). "As expected from the results presented above, inhibition of mtROS, and consequently, the induction of HIF-1α activity by the addition of MitoTEMPO, prevented the increase of glycolytic activity triggered by infection with the integrase-deficient HIV-1." (PMID 30206166, 2018). "To investigate the significance of HIF1α-dependent differentiation of pro-inflammatory macrophages during different pathogenic microorganism infections, we challenged WT and HIF1α−/− mice with L. monocytogenes in vivo at 48 h34,35." (PMID 29483608, 2018). "In accordance with the model that LDs are involved in macrophage production of eicosanoids during infection, inhibition of LD formation with T863 phenocopied the HIF-1α deficient BMDM for production of prostaglandins and LXB4." (PMID 29370315, 2018). "The improvements in bacterial clearance and inflammation were associated with a reduction in lung injury at 48 h post-infection, as assessed by histological methods, that was more pronounced in mice treated with HIF-1α stabilized MSCs." (PMID 29780805, 2018). "It showed that HIF1α deficient in myeloid cells decreased the bactericidal activity and exaggerated systemic spread of infection." (PMID 29483608, 2018). "Nevertheless, IFNγ-pulsed HIF-1α-deficient Ly6Chi/int monocytes were slightly more resistant to infection than wild type inflammatory monocytes." (PMID 28892492, 2017). "Moloney murine leukaemia temperature-sensitive virus and reovirus infections were shown to cause downregulation of HIF-1α expression." (PMID 27902314, 2016). "The authors conclude that bacterial siderophores account for the normoxic stabilization of HIF1A during infection with human pathogenic bacteria." (PMID 24086109, 2013). "Amongst infection related HIF-1 activation mechanism enterobacteriaceae infection causes HIF-1α stabilization by secreting iron-chelating siderophore." (PMID 22701652, 2012). "Various potential mechanisms underlie the elevation of HIF-1α in response to infection." (PMID 38539163, 2024). "These CNS complications could also be mediated by changes associated with the hypoxic state generated after infection and the activation of HIF-1α." (PMID 39203555, 2024). "Moreover, the role of HIF-1α was also indicated in favor of infection as it is associated with the induction of the M2 phenotype of myeloid cells." (PMID 38750790, 2024). "We further confirmed that intervention of HIF-1α–VEGFA signaling could mitigate infections caused by respiratory bacteria in mouse models, thereby presenting this pathway as a suitable candidate for therapy against respiratory bacterial infections." (PMID 36916939, 2023). "Our results demonstrated that P. multocida isolates of both human and animal origins could increase the permeability of respiratory epithelial barriers during infection, and this process was associated with the activation of the HIF-1α–VEGFA pathway." (PMID 36916939, 2023). "Analyses of multiomic data revealed that cardiomyocyte infection caused a rapid increase in genes and proteins related to activation innate and adaptive immune systems and pathways, including alpha and gamma interferons, HIF-1α signaling, and glycolysis." (PMID 36814444, 2023). "Hypoxia-inducible factor-1 alpha (HIF-1α) is a protein induced by hypoxia during inflammation and infection, and its upregulation may lead to the loss of tight junction proteins such as ZO-1, thereby damaging the integrity of the intestinal barrier." (PMID 37571299, 2023). "HIF-1α stabilization is necessary for immune responses against pathogens but is also associated with an exaggerated inflammatory response by inducing a cytokine storm and elevated chemotaxis of monocytes and neutrophils to the infection site." (PMID 36851739, 2023).
infection (continued). "Infection also caused an activation of glycolysis that was dependent on HIF-1α signaling." (PMID 36814444, 2023). "For instance, in Mycobacterium tuberculosis (Mtb)-infected mice, the blockade of HIF-1α during the early stage of infection, in which pro-inflammatory responses are critical to contain bacterial replication, results in higher susceptibility to infection." (PMID 35624725, 2022). "Myeloid cell HIF1α has been implicated in the regulation of cellular energy metabolism as well as immune responses and may play a role in host defense against infection." (PMID 34393650, 2021). "To further investigate the link between activation of HIF-1α and the metabolic reprogramming of macrophages, we assessed the impact of HIF-1α deficiency in response to infection using BMDMs from wild-type (C57BL/6) and myeloid-restricted HIF-1α-deficient (HIF-1c) mice." (PMID 32385235, 2020). "Hif-1α is a major transcriptional regulator of the cellular response to hypoxia, which has been implicated in the activation of macrophages and neutrophils during infection and inflammatory processes." (PMID 30552162, 2019). "In conclusion, we have shown that infection-induced systemic changes in carbohydrate metabolism are associated with changes of macrophage cellular metabolism, and that both can be affected by macrophage-specific Hif1α and Ldh knockdown." (PMID 31609200, 2019). "To determine whether HIF-1α-deficient monocytes were more resistant to infection by L. donovani, we infected bone marrow-derived monocytes in vitro with fluorescently labelled amastigotes and monitored the infection for 24h by FACS and Image Stream." (PMID 28892492, 2017). "Besides mutations, infection with oncogenic viruses has been reported to alter HIF-1α regulation, thereby contributing to the oncogenic phenotype." (PMID 27602585, 2016). "By depositing HIF-1α boosting agent directly into the bladder through a catheter, we could prevent infections and limit the risk of bladder and renal damage caused by acute inflammation." (PMID 25927232, 2015). "Moreover, HIF-1α was implicated in the expansion of myeloid-derived suppressor cells in the spleens of L. donovani-infected mice, further increasing susceptibility to infection." (PMID 40512023, 2025). "Furthermore, resistance to HIF-1α stabilization was evident by a significant increase in the IC50 associated with DMOG inhibition of oxidative phosphorylation in the presence of infection, suggesting that this critical pathway for detection of metabolic stress was limited by SARS-CoV-2." (PMID 37417946, 2023). "In addition, HIF1α stabilization by oxygen deficiency or infection might enhance wound healing and tissue repair." (PMID 33125509, 2021). "However, it is possible that in highly inflamed lungs, oxygen availability is impaired and HIF1α deficiency might impair AM functions at a later stage of the infection." (PMID 34393650, 2021). "Thus, in our studies we found that activated HIF1α-deficient NK cells upregulate the key pro-apoptotic protein Bim and its downstream targets during in vitro proliferative and pathogen infection responses to promote cell death while there was little evidence implicating other survival pathways." (PMID 34396954, 2021). "However, the significance of HIF1α-glycolytic pathway signals in protecting against different kinds of pathogenic microorganism infections remains unclear." (PMID 29483608, 2018). "To investigate whether glycolytic activity is involved in the HIF1α-directed macrophage differentiation during different pathogenic microorganism infections, we cultured and stimulated peritoneal macrophages from HIF1α−/−, WT, or 2-DG pretreated WT (WT; 2-DG) mice with either LPS or curdlan." (PMID 29483608, 2018). "Moreover, CD11c-specific HIF-1α deficient mice were highly resistant to infection." (PMID 29472618, 2018). "However, the role of macrophage HIF1α in protecting against different pathogenic infections remains unclear." (PMID 29483608, 2018).